KRAS (KRas proto-oncogene, GTPase)
Diseases named in the same sentence as KRAS in open-access papers (continued):
Sharing a sentence is not in itself a finding about the gene and the disease.
cancer (continued). "Our findings support the idea that treatment of KRAS-driven NSCLC and CRC, and potentially the other mutant KRAS driven cancers, may benefit from the concurrent inhibition of KRAS signaling and MYC." (PMID 28152508, 2017). "We sequenced specific exons of 16 cancer-related genes, including the most clinically relevant genes such as KRAS, NRAS, EGFR, BRAF, cKIT, as well as other targetable genes that are known to be somatically altered in solid cancers based on recent scientific and clinical literature." (PMID 28404952, 2017). "Both compounds also kill cancer cells expressing mutant oncogenic KRAS." (PMID 28807782, 2017). "Mutations in BRAF and KRAS, acting in the RAS-RAF-MAPK kinase cascade and mutated PIK3CA, acting in PI3K-PTEN-AKT signaling pathway, are known for their contribution to the development of CRC and are associated with cancer prognosis." (PMID 28125730, 2017). "Therefore, G2 checkpoint kinase inhibitors have been suggested as therapeutics for targeting KRAS-driven cancers." (PMID 28978051, 2017). "Given the variety of resistance mechanisms that arise in response to tyrosine-kinase inhibition in RTK-mutated cancers, it is unsurprising that multiple pathways could maintain PDAC cell survival following KRAS inhibition in various contexts." (PMID 29061961, 2017). "Since the RAS genes have several miRNA let-7 binding sites at the 3′-UTR, let-7 targets and regulates KRAS gene expression, and the reduction of let-7 in cancer tissues is correlated with higher KRAS mRNA expression, suggesting the regulatory roles of let-7 miRNAs in KRAS." (PMID 28441730, 2017). "Remarkably: (i) expression of KrasG12C isoform 2A conferred enhanced MPE competence to PANO2 cells compared with KrasG12C isoform 2B, although the later was more abundantly expressed by KRAS-mutant cancer cells; and (ii) mutant KRAS expression converted even benign HEK293T cells to MPE competence." (PMID 28508873, 2017). "Then, 2343 records were excluded because of the duplications or no information on KRAS mutation detected by cfDNA and survival in cancer patients through the screening of the titles and abstracts of all studies." (PMID 28796802, 2017). "We propose DNA2 inhibition as new strategy in cancer therapy by targeting replication stress, a molecular property of cancer cells that is acquired as a result of oncogene activation instead of targeting currently undruggable oncoprotein itself such as KRAS." (PMID 28414320, 2017). "This adds to our finding that they are potential KRAS synthetic lethal partners; their high expressions may sustain oncogenic KRAS signaling and knocking them down can have a big effect in cancer cell lines’ viability." (PMID 28415695, 2017). "The findings from this study also help us to understand whether the dual targeting of MEK and cancer metabolism may be a novel and effective strategy to tackle KRAS-mutant NSCLC." (PMID 28938614, 2017).
cancer (continued). "A 2nd cohort with added eligibility restrictions was accrued: prior therapies were limited to no more than 2 or 3 (KRAS-mutated and KRAS-wildtype cancers, respectively) and <30% of liver involvement." (PMID 28186961, 2017). "They compared histological specimens from the initial resection with specimens from the repeat resection by means of pyrosequencing assay for Kirsten rat sarcoma (KRAS) mutations and immunohistochemistry for mucin (MUC) 1 and MUC2 to distinguish between cancer recurrence and new primary lesion." (PMID 28716115, 2017). "Approximately two-thirds of human cancers, including skin, colon, lung, and pancreas; multiple myeloma; and hairy cell leukemia, have aberrations in the ERK1/2 cascade, largely due to activating mutations in signaling intermediates such as EGFR, KRAS, or BRAF." (PMID 28982763, 2017). "This study serves as the proof of concept that dual targeting of MEK and cancer metabolism may be a novel approach to tackle KRAS-mutant NSCLC." (PMID 28938614, 2017). "In the case of G12D KRAS mutant cancers, Akt inhibitors may sensitize to the MEK inhibitors but it seems we will need better compounds to be successful in the clinical setting." (PMID 28957417, 2017). "We compared KRAS copy numbers in patients with early‐stage cancer and healthy individuals; surprisingly, DNA fragments captured by standard ddPCR in patients with PDA were not larger than those from healthy controls when normalized by plasma cfDNA concentrations." (PMID 28691390, 2017). "Furthermore, we found that Nestin was related to KRAS activation and gene expression patterns thought to reflect cancer stemness, such as activation of Wnt/β-Catenin related pathways and retinol metabolism." (PMID 28439082, 2017). "Therefore, it is urgently needed to find effective inhibitors to target and inhibit oncogenic KRAS in cancers." (PMID 29184501, 2017). "Among many oncogenes, VEGFA, BCL2 and KRAS are overexpressed in many types of cancer cells." (PMID 28102286, 2017). "In addition, several different cancer cell lines bearing mutant oncogenic KRAS were sensitized by 2- to 4-fold to Poloppin after depletion of c-MET using siRNA." (PMID 28807782, 2017). "Our work suggests that in vitro KRAS assays that more closely mimic the cellular context may provide more relevant inhibitors in KRAS-dependent cancer cells." (PMID 28384226, 2017). "When subjected to gene set enrichment analysis based on the Hallmark gene sets, the five top-scoring categories (all with FDR q-value < 10-4) were associated with cancer-related processes such as epithelial-to-mesenchymal transition (EMT), TGF-beta signaling, TNFA signaling and KRAS signaling." (PMID 29228717, 2017). "In addition, Lin28B silencing in PDAC cells inhibited cell proliferation, cell cycle transition, migration and the EMT and increased the expression of the c-MYC, HMGA2 and KRAS genes, which are targeted by the cancer suppressor miRNA let-7." (PMID 28947981, 2017). "KRAS, first discovered in the rat sarcoma virus, plays a critical role in human cancer." (PMID 28212646, 2017). "In response to DNA damage or replication stress, KRAS-driven cancer cells activate G2 checkpoint kinases, such as ATR, Chk1, and Wee1, which might promote the survival of these cells." (PMID 28978051, 2017). "Consequently, MSI testing was performed directly by the molecular cancer genetics platforms for patients under 60 years old and/or BRAF-mutated CRC when there was KRAS/BRAF testing." (PMID 29137623, 2017).
cancer (continued). "However, some cancer cells upregulate TRAIL-R expression, and we recently showed that this facilitates progression of KRAS-mutated cancers via cancer cell-autonomous Rac1 activation independently of FADD." (PMID 28212753, 2017). "KRAS was among the first biomarker tests that became widely used to guide cancer treatment." (PMID 29202108, 2017). "Here, we have established multiple mutant KRAS-driven cancer cell lines with acquired resistance to the purine-scaffold HSP90 inhibitor PU-H71 to prospectively identify mechanisms through which HSP90-dependent cancer cells evade pharmacologic HSP90 blockade." (PMID 28032595, 2017). "KRAS signalling in cancer drives cell proliferation and promotes survival." (PMID 28163917, 2017). "Therapies that target mutant KRAS or PIK3CA proteins could also be investigated as prophylactic therapies in individuals with Noonan and Cowden syndromes, who have high cancer risk because they carry germline mutations in these genes." (PMID 28755461, 2017). "Similarly, KRAS, NRAS, HRAS all have highly recurrent activating mutations at position G12 (KRAS) in the Ras domain in a large variety of cancers." (PMID 28423505, 2017). "More importantly, this combination could serve as a proof-of-concept study to investigate the value of dual targeting MEK and cancer metabolism for KRAS-mutant NSCLC." (PMID 28938614, 2017). "KRAS-driven cancers remain refractory to current clinical therapies." (PMID 28220783, 2017). "Thus, we implicate the protein-protein interactions of PLK1 and PLK4 in the maintenance of mutant KRAS-expressing cancers, and illustrate the use of compounds that block these interactions in single-agent or combination therapies." (PMID 28807782, 2017). "Additional cancer mutations were detected in OV7 (FOXL2 p.C134W) and OV9 (KRAS p.G12V)." (PMID 28852190, 2017). "Additionally, INTS11 knockdown diminishes the MAPK responsiveness and cellular growth in A375 and A549, cancer cell lines with activating mutations in BRAF and KRAS, respectively." (PMID 28982763, 2017). "Furthermore, glutamine is also important to support cancer cells viability and growth through the KRas-regulated metabolic pathway." (PMID 28245869, 2017). "Our findings support a direct link between MYC and cancer cell viability, and raise the possibility that inactivation of MYC may be an effective therapeutic strategy for KRAS mutant tumors across various cancer types." (PMID 28152508, 2017). "While patient factors may contribute to receipt of KRAS testing, literature examining general adoption of cancer guidelines suggests the most important influence remains the ordering physician." (PMID 29202108, 2017). "Our results show the feasibility of applying the AmpliSeq hotspot cancer panel V2 on Ion TorrentTM to both live cells and fixed cells enriched from blood by ISET® and recovered in suspension, assessing mutations on a variety of oncogenes including KRAS." (PMID 28060956, 2017). "Additionally, African women displayed a notably higher risk of having cancers harbouring ERBB2 mutations (HR: 8.01; 95% CL: 2.41-26.68; p=0.001), and a lower risk of KRAS mutations (HR: 0.34; 95% CL: 0.13-0.89; p=0.027)." (PMID 28881604, 2017). "It has been reported that CRAF was involved in the MEKi resistance in KRAS mutant cancer cells." (PMID 28002807, 2017).
cancer (continued). "Indeed, the in vitro study showed that let-7 miRNA suppressed colon cancer growth and proliferation, in contrast, transfection with let-7a precursor miRNA significantly inhibited cancer cell growth and reduced the expression of KRAS and c-MYC." (PMID 28441730, 2017). "Visual inspection of the data, however, suggested that mutations reported to occur frequently in particular cancers showed large inter‐individual variability in the ACB‐PCR MFs in normal tissues (e.g., PIK3CA H1047R for breast, KRAS G12D for colon) [COSMIC, 2016]." (PMID 28755461, 2017). "This interaction regulates KRAS membrane association, which is crucial for RAS activity in cancer." (PMID 28815022, 2017). "Therefore, in this cell panel, engagement of senescence in KRAS mutant background also appeared to be specific for cancer cells." (PMID 28806777, 2017). "Next, we interrogated independent data sets of KRAS-driven cancers to determine whether the eight-gene signature would be a predictor for KRAS status." (PMID 28220783, 2017). "We searched for mutations in 22 cancer-related genes, using target sequencing techniques to further characterize the 12 patients who had AXL 3+ expression, of whom 6 had mutations in EGFR, 2 in KRAS, and 1 EML4–ALK fusion gene." (PMID 27100677, 2016). "Our findings increase the likelihood that the coordinate inhibition of synthetic lethal genes of oncogenic KRAS may provide a novel therapeutic approach for treating these recalcitrant cancers." (PMID 27193833, 2016). "Because these synonymous mutations in KRAS have been found in human cancers, we suggest that testing for the mutational status of KRAS in cancer patients should not systematically exclude synonymous codon replacements." (PMID 27684555, 2016). "Our findings suggest a drug combination that disrupts KRAS synthetic lethal dependency, which could be therapeutically exploited to inhibit KRAS-driven cancers." (PMID 27193833, 2016). "We believe that our conjugate is so effective at generating ROS in cancer cells that it is impossible for us to differentiate subtle differences that might exist between KRAS-mutant and KRAS-wildtype cancers." (PMID 27244881, 2016). "KRAS mutant cancer cell lines (HCT116 and Panc-1) were more sensitive to GSTO1 inhibition." (PMID 27703239, 2016). "All three missense KRAS mutations occurred at known hotspots of amino acid residues of position 12, 13 and 61 (G12D, G13D, Q61L in ICC26, ICC6, ICC41, respectively) as likely cancer drivers of three ICC cases." (PMID 27009864, 2016). "Moreover targeting metabolic Achilles' heels specific to KRAS isoforms will help in determining if a sufficient therapeutic window exists to spare normal cells and effectively target cancer cells." (PMID 27283493, 2016). "In addition to cancer, mutations in HRAS and KRAS genes have been associated with the Costello and Noonan syndromes, respectively." (PMID 27713118, 2016). "MEK inhibitors are the most effective agents in KRAS mutant cancer cell lines." (PMID 27014419, 2016). "For example, knocking down a specific gene of undruggable cancer, such as KRAS mutant adenocarcinoma of NSCLC, can activate a parallel dormant effector pathway that may be sensitive to a TKI3." (PMID 27530552, 2016). "The location of the primary tumor, age, sex, histology of cancer cells, presence of lymphatic/perineural invasion, KRAS and BRAF mutation, or EGFR and ERBB2 expression did not significantly influence the success of PDC establishment." (PMID 26909603, 2016).
cancer (continued). "Activating KRAS mutations are found in approximately 20% of human cancers but no RAS-directed therapies are currently available." (PMID 26881434, 2016). "Given the importance of synthetic lethal genes in buffering the effect of changes in KRAS, combinations of inhibitors that target these genes may be promising strategies to treat recalcitrant KRAS-mutant cancers." (PMID 27193833, 2016). "KRAS has long been considered a target for cancer therapeutics." (PMID 27322423, 2016). "By comparisons of doubling time and MDR between the mutant and wild-type NCI-60 cell lines, we revealed that mutations of APC, KRAS, and PIK3CA might correlate with enhanced malignancy of cancer cells." (PMID 26937901, 2016). "We hypothesized that there is a synthetic lethal interaction between p21 and KRAS, and that the elevated expression of p21 would suppress KRAS-mutant cancers." (PMID 27193833, 2016). "Given the prevalence of KRAS mutated cancers (predominantly pancreas, colon and lung) in the population, we cannot exclude that a small proportion of these individuals were non-diagnosed KRAS mutated cancer cases." (PMID 27705932, 2016). "MiR-134 down-regulation in cancer could consequently lead to RAS-MAPK pathway activation by mediating cooperative KRAS overexpression and HRAS activation." (PMID 26646588, 2016). "Finally, we showed that this combinatorial strategy, by targeting the synthetic lethal partners of the oncogene KRAS, is a potential novel and efficacious treatment of KRAS-mutant cancers." (PMID 27793187, 2016). "AKT1 and AKT2 are frequently activated in human cancer following loss of the lipid phosphatase PTEN, activating mutations and/or copy number variation in EGFR or HER2 tyrosine kinase receptors, activating mutations in KRAS, in PIK3CA or in AKT1 itself." (PMID 26859676, 2016). "We reported that mutations in some cancer driver genes mutations in some cancer driver genes such as APC, KRAS, or PIK3CA might correlate with cancer proliferation or drug resistance." (PMID 26937901, 2016). "Of the many RBPs that bind to the KRAS 3′ UTR, AGO2, HuR (or ELAVL1), IGF2BP1/2/3, PUM2, EWSR1, TAF15, FUS, and TIA1 have been previously implicated in cancer." (PMID 26930719, 2016). "For example, in cancer, the RAS genes HRAS and KRAS are frequently mutated." (PMID 27933272, 2016). "The KRAS/ K-RAS oncogene is crucially involved in human cancer." (PMID 27102293, 2016). "Moreover, Corcoran and collaborators identified, by a pooled shRNA-drug screen, a synthetic, lethal interaction of combined Bcl-xL and MEK inhibition to promote tumor regressions in KRAS mutant cancer models." (PMID 27019364, 2016). "The results of this study indicate that the addition of BKM120 may overcome cetuximab resistance in KRAS mutant CRC by targeting the PI3KCA pathway in patients with PI3KCA wild‐type cancers." (PMID 26715098, 2016). "The remaining nine surface proteins identified solely (ANTXR1, AG1, DCBLD2, EFNB1, EMB, OSMR, SLC1A5) or found upregulated (ATP1B3 and ITGB1) on the MCF10A surface had no direct association with embryonic development signaling in the context of KRas mutant signaling in cancer cell lines." (PMID 27894102, 2016). "Targeted deep-sequencing of 538 cancer-relevant genes was performed in 57 HD-ALL patients lacking overt KRAS and NRAS hotspot mutations and lacking common B-ALL deletions to enrich for discovery of novel driver genes." (PMID 27683039, 2016).